NFKB1 (nuclear factor kappa B subunit 1)
Diseases named in the same sentence as NFKB1 in open-access papers (continued):
Sharing a sentence is not in itself a finding about the gene and the disease.
teratocarcinoma (3 papers, 2013 to 2019). A germ cell tumor characterized by the presence of an embryonal carcinoma component and a teratoma component. "They reported that human stem cells and teratocarcinoma cells show a selective reduction in the expression of E2F1, E2F2, E2F3 and p105 (encoded by NFKB1) and enhanced expression of E2F4, E2F5, E2F6 and p130 (encoded by RBL2) compared with human normal somatic IMR90 cells." (PMID 24355041, 2013).
urolithiasis (3 papers, 2020 to 2021). Stone(s) within the urinary tract. "On the other hand, our group reported that both MCP-1 and NFkB1 enhanced expression correlated to changes in oxidative stress levels and Nox1 upregulation in an ethylene glycol-induced rat model of urolithiasis." (PMID 34064366, 2021).
urticaria (3 papers, 2023 to 2026). A vascular reaction of the skin characterized by erythema and wheal formation due to localized increase of vascular permeability. "At NFKB1, the risk allele for urticaria positively correlates with variants associated with higher RNA expression in neutrophils and adipose (r2 > 0.95) and increased plasma NFKB1 protein levels (rs230539[G]; r2 = 0.96)." (PMID 37430141, 2023).
Abdominal obesity (2 papers, 2013 to 2021). Excessive fat around the stomach and abdomen. "In men the combined effects of the NFKB1 - 94ins/delATTG promoter polymorphism and general or abdominal obesity showed a tendency towards positive interaction." (PMID 23671649, 2013).
alopecia (2 papers, 2014 to 2019). Hair loss usually from the scalp. "However, at 12 and 18 months, compared to age-matched Nfkb1+/+ animals, Nfkb1−/− mice have a higher incidence of several observable age-related characteris-tics including rough fur coat, alopecia, rectal prolapse and paraphimosis." (PMID 25553648, 2014).
chronic granulomatous disease (2 papers, 2016 to 2023). Chronic granulomatous disease (CGD) is a rare primary immunodeficiency, mainly affecting phagocytes, which is characterized by an increased susceptibility to severe and recurrent bacterial and fungal infections, along with the development of granulomas. "It has also been described in genetically diverse IEIs including ataxia telangiectasia, NFKB1 haploinsufficiency, ADA2 deficiency, CD40 ligand deficiency, activated PI3K delta syndrome, STAT3 gain of function and chronic granulomatous disease (CGD)." (PMID 38068532, 2023).
essential hypertension (2 papers, 2022 to 2023). Hypertension that presents without an identifiable cause. "A population-wide genomic study showed that NFKB1 is a susceptibility gene for primary hypertension." (PMID 35655614, 2022).
lichen sclerosus (2 papers, 2019 to 2022). "Since the NFKB1/2 factors are activated via different inflammatory molecules, we aimed to check their expression levels in penile cancer (PC), penile dermatoses: lichen sclerosus (PLS) and zoon balanitis (ZB)." (PMID 36555871, 2022).
necrotizing fasciitis (2 papers, 2023 to 2024). "Family members of this report suffered from recurrent necrotizing fasciitis or intense wound inflammation in association with heterozygous NFKB1 p.R157X variant." (PMID 36892687, 2023). "In fasciitis patients with a known underlying truncating NFKB1 mutation, anti-inflammatory therapies, including glucocorticoids and/or IL-1β targeting therapies or JAK inhibitors, could be beneficial in reducing excessive inflammation and the need for surgical revisions and amputations." (PMID 38593810, 2024). "In summary, the NFKB1 c.C936T/p.R157X LOF variant has an impact on inflammation and neutrophil function and may play a role in the pathogenesis of sterile necrotizing fasciitis." (PMID 36892687, 2023). "However, with thus far used methods here and in literature, aberrant adaptive immunity in NFKB1 pathogenic mutation carriers with fasciitis has not appeared to contribute to the development of necrotizing fasciitis." (PMID 36892687, 2023).
neurofibroma (2 papers, 2024 to 2025). An intraneural or extraneural neoplasm arising from nerve tissues and neural sheaths. "Instead, Nfkb1 deletion significantly delays neurofibroma formation in the mice, indicating a promoting role of NF-κB1 in Tax-driven neurofibromatosis." (PMID 38722890, 2024). "In line with previous studies showing the role of NF-κB in promoting neurofibromas driven by Tax, Nfkb1 deletion inhibited neurofibroma development in Tax+ mice." (PMID 38722890, 2024).
neurofibromatosis type 1 (2 papers, 2022 to 2025). A clinically heterogeneous, neurocutaneous genetic disorder characterized by cafe-au-lait spots, iris Lisch nodules, axillary and inguinal freckling, and multiple neurofibromas. "This microRNA also has a proven role in regulating tumorigenesis in the neurofibromatosis type 1 by involving in the NFKB1-miR-612-FAIM2 signaling pathway." (PMID 35581633, 2022).
penile cancer (2 papers, 2022 to 2024). A primary or metastatic malignant neoplasm that affects the penis. "The presented data partially correspond with our observations of increased NFKB1 level in penile cancer tissue." (PMID 36555871, 2022). "Results obtained in the present study showed high overexpression of NFKB1 mRNA in penile cancer." (PMID 36555871, 2022). "Furthermore, there is a high overexpression of NFKB1 mRNA in penile cancer and NFKB2 mRNA in penile lichen sclerosus, which shows an implication of the NF-kB pathway in penile cancer and some dermatoses." (PMID 39202278, 2024).
rectal adenocarcinoma (2 papers, 2022 to 2025). "Our study shows that multiple immune genes associated with ASCC3, including JAK1, NFKB1, SEMA5A, NR2C2, CNTF and CREB1, positively impact the prognosis of rectal adenocarcinoma patients." (PMID 40881169, 2025). "ASCC3 is a specific protective factor for rectal adenocarcinoma across various cancer types, particularly in digestive system cancers, and can synergize with several immune-related genes, including JAK1, NFKB1, SEMA5A, NR2C2, CNTF, and CREB1, to influence patient prognosis." (PMID 40881169, 2025).
xerostomia (2 papers, 2022 to 2024). Dryness of the mouth resulting from reduced salivary secretion. "The PPI network genes IL6R, EGFR, NFKB1, MPO, and TNFSF13B constitute a possible biomarker signature of xerostomia." (PMID 35268532, 2022). "The IL6R, EGFR, NFKB1, MPO, and TNFSF13B genes might all have implications in the diagnosis and intervention of xerostomia." (PMID 35268532, 2022).
adrenal tumors (1 paper, 2024). "It is thus of interest to examine whether the human primary adrenal tumors were derived from macrophages like those in Nfkb1-/-/Tax+ mice." (PMID 38722890, 2024).
carcinoma in situ (1 paper, 2020).
meningococcal meningitis (1 paper, 2021). "An association between meningococcal meningitis and NFKB1 is not reported yet." (PMID 35003082, 2021).
oligospermia (1 paper, 2018). Decreased number of spermatozoa in the semen. "Therefore, we investigated the single or combined effects of NFKB1 rs28362491 and tested if its regulator miRNA, pre-mir-146a rs2910164 is related to the susceptibility to oligospermia in a Turkish population." (PMID 29942932, 2018). "Hereby, we hypothesized that the relationship between E-cadherin expression and oligospermia risk could be changed by rs28362491, that is, a common functional polymorphism in NFKB1 gene." (PMID 29942932, 2018). "In other words, del/ins rs28362491 genotype could have a protective role in the case of fertilization in idiopathic oligospermia, whereas ins/ins and del/del genotype of NFKB1 could be a risk factor." (PMID 29942932, 2018).
penile diseases (1 paper, 2022). "Therefore, the main goal of the present study was to check the basic parameter of NF–κB signaling at the mRNA expression levels of the main downstream activators, NFKB1 and NFKB2, in penile diseases." (PMID 36555871, 2022).
tumor (10,484 papers, 2002 to 2026). "In terms of inflammatory factors, IL6, IL1B, and NFKB1 expression levels were notably reduced in the combination treatment group relative to the control group, suggesting a potential reduction in tumor-associated inflammation." (PMID 40361560, 2025). "In WT tumor cells, regulons associated with NFKB1, XBP1, JUN, SREBF2, and EHF exhibited elevated activity." (PMID 40767963, 2025). "NFKB1 plays critical roles in tumor cell invasion and metastasis, with its expression linked to invasion and metastasis across various cancer types." (PMID 41048344, 2025). "Functional analysis revealed that NFKB430 acts as a tumor suppressor, and the mutation in NFKB1 weakened its tumor suppressive function." (PMID 37821906, 2023). "The function of NFKB1 in the cancer context is still not completely understood and has been linked from inflammation and tumor development to the induction of apoptosis." (PMID 36224313, 2022). "Cell therapy using Ikbkb or Nfkb1-deficient macrophages favors strong anti-tumor immunity and tumor rejection." (PMID 33572260, 2021). "Conversely, pro-inflammatory Nfkb1-/- macrophages adopt an anti-tumour phenotype that reduces the tumour burden in mouse models of colitis associated cancer." (PMID 34721373, 2021). "We found that a somatic missense mutation (G430E) in NFKB1 showed significant increased mutant allele frequency in tumour cells after radiotherapy." (PMID 29484114, 2018). "Several members of the canonical NF-κB pathway were in the top list, including RELA, NFKB1, CHUK, IKBKB, IKBKG, and REL, indicating that the canonical NF-κB pathway was closely associated with immune-related DEGs in tumour serum-cultured DCs." (PMID 28350008, 2017). "We further analyzed the combined genotypes of the NFκB1 and NFκBIA polymorphisms by examining age, sex, smoking, drinking, BMI, tumor site, and family history of cancer by logistic regression." (PMID 21738780, 2011). "Our findings suggest a possible association of this polymorphism with modulation of NFKB1 expression, which might interfere with tumor cell growth control and inhibition of apoptosis, leading to the more aggressive behavior of cHL." (PMID 33684151, 2021). "In addition, we find for the first time that 5FU followed by three doses of p50KO‐IMC, generated by gene editing the Nfkb1 alleles in WT marrow and then expanding cells in serum‐free media, is also effective at slowing tumor growth." (PMID 33480449, 2021). "Furthermore, female HCC patients carrying the NFKB1 -94 Ins polymorphism were associated with lower clinical stages and smaller tumor sizes." (PMID 23457512, 2013). "The interaction between estrogen and NF-κB activities could in part explain the inverse correlation between -94 Ins polymorphism in the NFKB1 promoter and the clinical stage and tumor size in female patients." (PMID 23457512, 2013). "NFKB1 mRNA levels were lower in both tumour and normal tissue from cancer patients (P<0.001) as compared to healthy individuals but we were unable to show association between NFKB1 -94ins/del genotype and NFKB1 mRNA levels." (PMID 23977225, 2013). "Given the phospho-dependent interaction of p50 with BARD1, it would be interesting not only to examine p50 in these mice, but also to evaluate whether they have altered susceptibility to carcinogen-induced tumor formation, as was previously seen with Nfkb1-/- mice." (PMID 33024116, 2020). "Using this cohort, we determined the correlation between RELA and NFkB1 expression levels from 24,489 tumor cells." (PMID 41285837, 2025). "In conclusion, EBV-induced LINC00944 contributes to OSCC progression by enhancing tumor cell migration, invasion, and macrophage differentiation, potentially regulating these processes through NFKB1 and RELA." (PMID 39941858, 2025). "Key proteins identified, including ANXA1, SLC2A1, S100A4, and NFKB1, contribute to tumour progression and the resistance phenotype." (PMID 40004024, 2025).
tumor (continued). "NFKB1, a central player in the NF‐κB signalling pathway, has been pinpointed as a tumour‐promoting agent that fosters tumour cell growth and angiogenesis." (PMID 41275425, 2025). "In turn, activated astrocytes secrete factors such as TGF-β, which amplify NFκB1 signaling in tumor cells through a feedforward mechanism, promoting their chemoresistance." (PMID 40149331, 2025). "Hematoxylin and eosin (H&E) staining revealed a tumor histology in the medulla of the giant adrenal glands of Nfkb1-/-/Tax+ mice." (PMID 38722890, 2024). "S16, B and D) and strong inflammation-related TF activation, including Irf1 and Nfkb1, akin to previously reported tumor-infiltrating CCR7+ DCs that secrete IL-12 and activate T cells to increase antitumor activity." (PMID 37075115, 2023). "Our functional analyses indicated that NFKB1-mediated NOTCH activation supported the survival of the tumor cells." (PMID 36009586, 2022). "Various secreted factors associated with TAMs are also potential biomarkers, such as Tim-3 which correlates with increased tumour invasion and lymph node metastasis and CCL5/RANTES and NFKB1 where SNPs are associated with altered clinical outcome." (PMID 36139540, 2022). "The highest level of NFKB1 expression was observed in tumor PC samples (ca. 22 and four times higher than in controls and normal foreskin samples)." (PMID 36555871, 2022). "We also noted indications of an inflammatory response and TGF signaling in tumor-draining LN fLECs, including an upregulation of Nfkb1 expression and an enrichment of IRF1- and SMAD2-binding motifs." (PMID 35892863, 2022). "It facilitates the polarization of TAMs to M2 phenotype, which can release IL6 and CXCL8 to increase the expression of TNF in CRC cells, leading to the activation of NFKB1 pathway and then promotes tumor angiogenesis and metastasis." (PMID 35186730, 2022). "STAT3 is one of the major mediators of tumor-induced immunosuppression and was activated in MES-like state tumor cells, and NFKB1, an inflammatory regulon, was also upregulated in MES-like cells." (PMID 35669791, 2022). "In contrast, NFκB1 also acts as a tumor suppressor in some tumors, such as hepatocellular carcinoma and gastric cancer." (PMID 35896012, 2022). "(A–C) Box plots of MYC (A), NFKB1 (B), and STAT3 (C) expression in tumor-associated stroma from the GSE14548 dataset by disease grade (grade 1: G1; grade 2: G2; grade 3: G3)." (PMID 34169837, 2021). "Reduction of proteins encoded by NFKB1 and PIK3CA have been shown to aid in tumor survival and growth." (PMID 34968392, 2021). "With increasing levels of tumor PD-L1, the expression of transcription factors for Th1, Th2, or M1 macrophages, including NFKB1, GATA3, HIF1A, STAT4, TBX21, IRF8, and STAT1, was downregulated." (PMID 33754038, 2021). "HPV16 E1-mediated suppression of Nuclear factor-κB Subunit 1 (NFKB1) has also been shown to result in tumor growth." (PMID 34968392, 2021). "Treatment with a neutrophil-depleting antibody (anti-Ly6G) reduced tumour growth considerably in Nfkb1−/− mice." (PMID 30205516, 2018). "In ovarian cancer, miR-9 also targets NFKB1 and its downregulation in this cancer type, as compared to normal ovarian tissue is considered an additional tumor-promoting mechanism." (PMID 29601548, 2018). "In GC, miR-9 has been reported to be mainly downregulated, functioning as a tumor suppressor by targeting RAB34 (encoding the Ras-related protein RAB-34) and NFKB1 (encoding the NF-kappa-B transcription factor) oncogenes." (PMID 29879907, 2018). "Considering that this tumour patient was persistent infected with HPV, the somatic mutation in NFKB1 gene was very likely to cause the radiotherapy resistance in this study." (PMID 29484114, 2018). "Mechanistically, it was revealed that the NFKB1 targeting miRNA miR-508-3p was downregulated in GC cells, suggesting a tumour-suppressive function for this miRNA." (PMID 30205516, 2018).
tumor (continued). "In contrast, both NFKB1 and p65 have been shown at higher levels in GC cell lines and primary human GC tumours when compared to normal gastric epithelial cells which correlated with poor survival in patients." (PMID 30205516, 2018). "Nfkb1 mediates a chronic pro-inflammatory tumor microenvironment and constitutes a missing link between inflammation and cancer." (PMID 29109723, 2017). "NFKB1 protein expression shows negatively correlation with miR-508-3p in tumor tissues by Pearson correlation analysis (P = 0.033)." (PMID 26801246, 2016). "TGM2 was also reported to be upregulated in cancer cell lines by several important signaling pathways involved in tumor progression or metastasis, such as NFKB1/NF-κB, TGFB1/TGF-beta, RARA/RAR-alpha, and upon genotoxic stress." (PMID 26956429, 2016). "Identification of NFKB1 as a direct target of tumor suppressor miRNA miR-508-3p was achieved by expression regulation assays together with dual luciferase activity experiments." (PMID 26801246, 2016). "In contrast, Bromo-deoxy-uridine induced senescent NB-cells secret a tumor-promoting SASP in a NFKB1/p50-dependent manner." (PMID 26657295, 2016). "Characteristic cytoplasmic and nuclear staining was observed for NFkB1 in the majority of tumor specimens (stage I–IV)." (PMID 26388988, 2015). "A higher proportion of females carrying the NFKB1 -94 Ins polymorphism were in stage I/II than in stage III/IV (84.4% vs. 15.6%, respectively); tumor sizes also presented similar results (≤T2 vs. >T2; 87.5% vs. 12.5%, respectively)." (PMID 23457512, 2013). "In this study, we attempted to determine the importance of NFKB1 and NFKBIA gene promoter polymorphisms to the occurrence of HCC in Taiwanese and evaluated their relevance by correlating them with tumor clinicopathological characteristics." (PMID 23457512, 2013). "Within this pathway, NFKB1 plays a central role in tumor development." (PMID 41439108, 2025). "Second, except for CD38, NFKB1, and STAT4, the underlying mechanisms of the other five genes in OC progression and the tumor immune microenvironment remained largely unknown and required further investigation." (PMID 41141246, 2025). "In summary, this study identified JUN, NFKB1, and SP1 as important biomarkers associated with stem cells and telomere maintenance mechanisms in BC, highlighting their critical roles in tumor progression, alterations in the immune microenvironment, and potential therapeutic targets." (PMID 40666524, 2025). "The downregulation of JUN and NFKB1 in mesenchymal subtypes may impair their ability to maintain tumor-suppressive functions, highlighting their potential role in driving BC progression." (PMID 40666524, 2025). "Conversely, genes implicated in tumor progression, including Arghef18 and NfκB1, were downregulated in HPV transgenic mice lacking Klk5 and Klk7." (PMID 40753921, 2025). "Notably, the enhanced cytotoxic activity (CD8A, CD8B, and NFKB1) observed in irradiated T cells suggests a potential mechanism contributing to the improved tumor control observed in our study." (PMID 39445067, 2024). "Although most TFs have traditionally been regarded as “undruggable” targets, current research has revealed that the tumor therapy drug Binimetinib may have a potential targeted binding impact with NFKB1." (PMID 38273392, 2024). "Significantly, in the early stages of tumour development, both NFKB1/RELA and PIEZO1 displayed heightened expression levels, paralleled by similar kinetic trends of proliferation‐associated genes such as CDK6, CCND1 and CCND3, as unveiled by functional pseudotime analysis of the scRNA‐seq dataset." (PMID 37983931, 2023). "Moreover, the mRNA expression of miR-497/ NFkB1 /Ki67/ CD147/MMP-2 pathway in tumor were measured by RT-qPCR." (PMID 35896012, 2022).